APC (APC regulator of Wnt signaling pathway)
Diseases named in the same sentence as APC in open-access papers (continued):
Sharing a sentence is not in itself a finding about the gene and the disease.
colorectal cancer (continued). "In APC-mutated colorectal cancer cells, TNKSi resulted in the accumulation of cytoplasmic puncta and β-catenin degradasomes containing TNKS1/2, AXIN1/2, APC, GSK3β, and β-catenin." (PMID 34337362, 2021). "Over the years, this model has been tested, improved, characterized, and used to understand the role of the APC gene in colorectal cancer and also in chemopreventive studies." (PMID 33916402, 2021). "When evaluated in terms of stages, while the increase in the mRNA level of the APC gene in the peripheral blood samples of the patients in colorectal cancer stage III, the decrease in stage IV tumor tissues was significant." (PMID 33237662, 2021). "It was well documented that APC involves the pathogenesis of various cancers including colorectal cancers, pancreatic duct adenocarcinoma, oral cancers, breast cancers." (PMID 34344448, 2021). "We first confirmed that knockdown of β‐catenin in the APC‐mutant colorectal cancer cell line COLO320HSR markedly reduced the expression of BRCA1, FANCD2, and RAD51." (PMID 33660437, 2021). "The colorectal cancer mouse model was established by knocking down APC expression in normal epithelial cells taken from mouse intestinal crypts using short hairpin RNA (shAPC)." (PMID 34548081, 2021). "The initial event in most colorectal carcinomas (CRCs) is biallelic inactivation of the tumour-suppressor gene Adenomatous polyposis coli (APC)." (PMID 33809306, 2021). "A recent interrogation of the cBioPortal for Cancer Genomics database highlights APC, AXIN2, and β-catenin mutations in ≈67%, ≈5%, and ≈6% of colorectal carcinomas, respectively." (PMID 34352208, 2021). "APC is one of the key members of the WNT pathway and was previously reported to be mutated in approximately eighty percent of colorectal cancers." (PMID 33194656, 2020). "These genetic alternations are relevant as both APC and PIK3CA mutations are commonly present in human colorectal cancers." (PMID 32170841, 2020).
colorectal cancer (continued). "Reintroduction of full-length APC in a SW40 colorectal cancer cell line that expresses truncated APC restores normal morphology, cell-cell adhesion and migration in wound healing assays." (PMID 33348689, 2020). "Of note, this ability to respond to Wnt ligand distinguishes β-catΔS45-mutant colorectal cancer cells from the APC-mutant colorectal cancer cells." (PMID 32751567, 2020). "As a proof-of-concept, treatment with the antibiotic erythromycin resulted in the restoration of APC activity, a decrease in adenoma size and burden in a pool of colorectal cancer patients." (PMID 33348689, 2020). "The APC-COMMD10 fusion in colorectal cancer is one example wherein fusion-mediated truncation leads to a loss-of-function of tumor suppressors." (PMID 32493417, 2020). "In colorectal cancer, as the most abundant isoform of the PRDXs in the tumor tissues 75, PRDX2 was reported to be a tumor-promoter in colorectal cancers with APC mutation." (PMID 32231717, 2020). "Given the central importance of APC in colorectal cancer and its potential as a therapeutic target, it is of great interest to achieve a comprehensive understanding of the multiple mutations in Apc and their functional impact at the molecular level." (PMID 33348689, 2020). "Using quantitative imaging based on the detection of membrane-associated E-cadherin, we undertook a protein coding genome-wide siRNA screen to identify genes that regulate cell surface E-cadherin in the APC-defective colorectal cancer cell line SW480." (PMID 33057364, 2020). "Our study has implications both for the sequencing of the APC gene in early-onset colorectal cancer and for the etiology of this disease." (PMID 33352971, 2020). "Alterations in the tumour suppressor Adenomatous polyposis coli (APC) have been found in more than 85% of colorectal cancer cases." (PMID 33348689, 2020). "To investigate this issue, we employed CRISPR/Cas9 to introduce biallelic RNF43 PTCs in SW480 APC‐mutant colorectal cancer cells, in which RNF43 is actively transcribed (Fig EV2A and B)." (PMID 32965059, 2020). "Having demonstrated that β-catΔS45 still shows evidence of regulation by Wnt and APC, we turned our attention back to human colorectal cancer patient samples." (PMID 32751567, 2020). "BUB1B perfoms a role in the inhibition of APC expression, established as a tumor suppressor gene in most colorectal cancers." (PMID 30778371, 2019).
colorectal cancer (continued). "ASE of APC and TGFBR1, for example, is known to be associated with colorectal cancer (CRC), with the frequency of ASE in both APC and TGFBR1 reportedly increased up to 10-fold in CRC compared to controls." (PMID 31093489, 2019). "We then developed an anti-DKK2 antibody for the immunotherapeutic treatment of colorectal cancer with APC mutaions." (PMID 31372243, 2019). "Mutations in WNT signaling components, such as APC, AXIN, β-catenin, and WNT ligands were first observed in colorectal cancers, but have also been reported in other solid tumors and hematological malignancies, including leukemia and Multiple Myeloma (MM)." (PMID 31921125, 2019). "On that basis, UBE2N was identified, validated and discussed as a factor that maintains genomic stability and plays an important role in colorectal cancer development in close relation to β-catenin, APC and Wnt signaling." (PMID 31319803, 2019). "We have successfully developed a viable animal model of KRAS mutated colorectal cancer with tamoxifen inducible tumors harboring KRAS and APC mutations." (PMID 31766149, 2019). "Our model includes mutations in APC and KRAS, and therefore represents the most common genetic alterations detected in human colorectal cancer specimens." (PMID 31766149, 2019). "Given the interest in using tankyrase inhibitors to target APC mutant colorectal cancers (CRC), we also assessed MSC2504877 sensitivity in a panel of CRC tumour cell lines." (PMID 30655555, 2019). "Colorectal cancer (CRC) is initiated when the colonic epithelial loses the function of the adenomatous polyposis coli (APC) pathway which is essentially a part of Wnt signaling pathway." (PMID 31766149, 2019). "One of these genes is APC+/−, in which the human phenotype includes colorectal polyposis (leading to colorectal cancer); the murine APC+/− mutant, however, develops small intestinal polyps." (PMID 30915276, 2019). "Similar surveillance programmes are available for patients with genetic syndromes predisposing to colorectal cancer, such as Lynch syndrome (mutation in one of the DNA mismatch repair genes) and familial adenomatous polyposis (FAP; mutation in the APC gene)." (PMID 30677217, 2019). "The same is expected in the great majority of colorectal carcinomas whose APC truncations, like Apc1332T, retain binding to β-catenin and regulating its activity." (PMID 30760710, 2019). "It is reported that 5-Aza-dC was used in colorectal carcinoma cell lines for APC gene, which methylation promoted the migration and proliferation abilities." (PMID 30683109, 2019). "Inhibition of NUAK2 with WZ4003 blocked nuclear accumulation of YAP/TAZ in SW480, an APC mutant colorectal cancer cell line, as well as in TCCSUP, T24, and RT112, three bladder cancer-derived lines." (PMID 30158528, 2018).
colorectal cancer (continued). "The present study adds evidence that canonical WNT signaling represses distinct target genes in human colorectal cancers and that APC antagonizes WNT repression at these loci." (PMID 30131849, 2018). "The observation that APC truncations in human colorectal cancers increase total β-catenin levels suggests that APC has a direct role in β-catenin degradation." (PMID 29495399, 2018). "Mutations in Wnt pathway components such as adenomatous polyposis coli (APC) result in pathological disturbances, especially in colorectal cancer." (PMID 29793495, 2018). "YAP/TAZ are required for the growth of adenomas following APC inactivation, and elevated YAP/TAZ expression is associated with poor prognosis in colorectal cancer patients." (PMID 29652830, 2018). "In MSI colorectal cancers, RNF43 mutation is more frequent in the MLH1me+ than MLH1me− group, whereas APC/β-catenin mutation is more frequent in the latter." (PMID 29652830, 2018). "Colorectal cancers occurring in proximal and distal intestinal regions have different preferred APC genotypes, with a total of 2–3 and 0–2 intact 20 AARs, respectively." (PMID 29652830, 2018). "Super-resolution microscopy of Axin and APC complexes assembled after overexpression in colorectal cancer cells provided the first look inside the active destruction complex." (PMID 29641560, 2018). "Loss of APC predisposes for colorectal cancer partly because it suppresses oncogenic β-catenin/TCF-driven transcription, but also because APC regulates DNA repair and chromosomal stability." (PMID 30131940, 2018). "The fact that intratumor heterogeneity arises at a premalignant stage from the convergence and admixtures of multiple crypts harboring different APC and KRAS mutations provides fundamental data on the mechanism of the initial evolution of colorectal cancers." (PMID 29652830, 2018). "APC gene and Wnt signaling are considered as the key molecule and pathway for colorectal cancer initiation, and these findings greatly undermine their importance in tumor progression for Chinese patients." (PMID 29937994, 2018). "The altered expressions of EphB2 and EphB4 in colorectal cancer have been explained by changes in adenomatous polyposis coli (APC) suppressor gene activity, CBP complex, and Wnt pathway." (PMID 29682554, 2018). "APC (adenomatous polyposis coli) is a tumor suppressor gene best known for its roles as a negative regulator in the Wnt signaling pathway and in colorectal cancer." (PMID 29401736, 2018). "A mouse model of colorectal cancer whereby APC can be conditionally suppressed provided clear evidence that APC restoration drives rapid tumor cell-differentiation and regression without the relapse and restoration of a normal crypt-villus homeostasis." (PMID 29652830, 2018). "MALL, PHLDB2 and other genes responsive to APC are consistent with the emerging role of canonical WNT signaling targets in colorectal cancer invasion and progression, in addition to the better-characterized role of the pathway in colorectal tumor initiation." (PMID 30131849, 2018). "MiR-135-5p, one of the miRNAs found to be upregulated in cells treated with serum from HNSCC patients, targets the tumor suppressor APC and promotes cell growth in colorectal cancer." (PMID 29942793, 2018).
colorectal cancer (continued). "To further verify that the GFP tag on Axin does not alter its function, we analyzed Axin self-assembly in cultured colorectal cancer cells, where Axin self-assembles into multiprotein “puncta” and recruits APC into these structures." (PMID 29641560, 2018). "While this offered insights into the assembly ability of Axin and APC2, it involved very significant overexpression in an APC mutant colorectal cancer cell line." (PMID 29641560, 2018). "Mutations in the adenomatous polyposis coli (APC) oncogene-related pathway mediate the transition of single preneoplastic cells to aberrant crypt foci (ACF), and then to adenoma and colorectal carcinoma." (PMID 29439531, 2018). "Losses in 18q21.2, 5q21.1, and 17p12 loci were associated with reduced protein levels of three important colorectal cancer drivers: SMAD4; APC; and MAP2K4, respectively (FDR < 0.1)." (PMID 28854368, 2017). "Mutations involving components of the Wnt signaling cascade, especially in APC or β-catenin, are essential for initiation of many cancers, including colorectal cancer." (PMID 29050252, 2017). "Hyperactivation of Wnt signaling initiates colorectal cancer, which most frequently results from truncation of the tumor suppressor Adenomatous polyposis coli (APC)." (PMID 28708826, 2017). "Equally prominent were genes PIK3CA (44%) in breast, KRAS (51%) in lung, and APC (70%) in colorectal cancers." (PMID 28371134, 2017). "The Wnt signaling pathway is regarded as a key event in initiation of colorectal cancer in which APC plays an important role." (PMID 27880935, 2017). "EB1 is a binding protein of the tumor suppressor gene APC (adenomatous polyposis coli) which is known to play an important role during colorectal cancer development." (PMID 28903393, 2017). "Adenomatous polyposis coli (APC) promoter hypermethylation has been frequently observed in colorectal cancer (CRC)." (PMID 28515349, 2017). "Wnt pathway hyperactivation is a near ubiquitous feature of colorectal cancer (CRC), most frequently caused by truncating mutations in the adenomatous polyposis coli (APC) tumour suppressor." (PMID 28695896, 2017). "Colorectal cancer (CRC) is among the most common and fatal forms of solid tumors worldwide and more than two thirds of CRC and adenomas patients have APC gene mutations." (PMID 29050326, 2017). "Mouse Apcmin, truncated at codon 850 produces a much shorter APC protein than those typical of human colorectal cancer." (PMID 28708837, 2017). "In selenite-treated colorectal cancer cells, We showed that selenite promotes binding of APC/C-CDH1 with GLS1, which targeted GLS1 for further degradation." (PMID 27902968, 2017). "APC is required in the gastrointestinal tract and serves as a gatekeeper that prevents colorectal cancer." (PMID 28708826, 2017). "Some of these variants occur within genes related to diseases that are known to be more commonly diagnosed in the AJP than in NJPs: colorectal cancer (APC gene) and pancreatic cancer (HGFAC gene)." (PMID 28502252, 2017). "To further test the validity of our network model, we have simulated the cancer reversion for colorectal cancer network models by restoring the basal level of APC." (PMID 28381275, 2017). "Multiple hits in the same gene were observed for colorectal cancer cases (34%), particularly in APC gene." (PMID 28371134, 2017).